MMP9 (matrix metallopeptidase 9)
Diseases named in the same sentence as MMP9 in open-access papers (continued):
Sharing a sentence is not in itself a finding about the gene and the disease.
polymyositis (5 papers, 2012 to 2022). A rare idiopathic inflammatory myopathy characterized by symmetric proximal muscle weakness and elevated muscle enzymes. "High MMP-1 and MMP-9 expression was detected in myositis, polymyositis, and dermatomyositis patients, and MMP-9 antibodies are found in nearly all inflammatory myopathies." (PMID 36289739, 2022). "In the diseased muscle biopsies obtained from patients with polymyositis and dermatomyositis, MMP9 was shown to be overexpressed in the endomysial inflammatory cells and regenerating muscle fibers." (PMID 31440381, 2019). "MMP9 level was shown to be increased in the muscle fibers and around auto-invasive CD8+ T lymphocytes in patients with polymyositis." (PMID 31440381, 2019). "Although, in some inflammatory myopathies, such as polymyositis, dermatomyositis, and inclusion body myositis, both MMP-2 and MMP-9 are upregulated, their balance depends on the type of disease and local presence of various factors." (PMID 28042204, 2016). "In addition, overexpression of MMP-9, and MMP-1 was detected in dermatomyositis and polymyositis." (PMID 36289739, 2022). "Moreover, MMP9 expression was shown to be increased in the muscle membranes of MHC class-I-expressing muscle fibers and auto-invasive CD8+ T lymphocytes in the muscle biopsy specimen obtained from a patient with polymyositis." (PMID 31440381, 2019).
respiratory infections (5 papers, 2015 to 2025). "Matrix metalloproteinase-9 (MMP-9) plays a crucial role in modulating inflammatory responses during respiratory infections." (PMID 35892136, 2022). "Investigation of plasma MMPs in other respiratory infections have shown that plasma MMP-9 is elevated in community acquired pneumonia compared to healthy controls and in two studies, MMP-9 was found to return to normal after antibiotic treatment." (PMID 25635689, 2015). "Additionally, several published studies in adult populations have reported elevated MMP-9 levels in various respiratory infections, such as community-acquired pneumonia." (PMID 40558582, 2025). "In a study of 171 healthy British Bangladeshi adults, vitamin D levels were inversely correlated with circulating MMP-9 levels, while a vitamin D metabolite (1α,25(OH)2D3) was found to inhibit MMP-9 gene expression, secretion, and activity in the setting of various respiratory infections." (PMID 33800947, 2021). "Given RBP1 is critical for retinol transport and MMP9 plays a role in immune cell recruitment and lung tissue repair, these findings suggest Zn supplementation may support processes vital for vitamin A metabolism and tissue repair during a subclinical respiratory infection." (PMID 40927235, 2025).
retinal degeneration (5 papers, 2016 to 2023). Degeneration of the retina. "Specifically, matrix metalloproteinase gelatinase B (MMP-9, GelB) has been implicated in retinal degeneration." (PMID 36768896, 2023). "Our previously published work in rd1 mouse and S334ter-line-3 transgenic rat retina provides convincing evidence that MMP-9 inhibitors have both a positive neuronal cell survival effect and a therapeutic potential to slow rod cell death, which is the initial hallmark of retinal degeneration." (PMID 34270579, 2021). "MMP-9 is rarely detected in healthy retina; however, the upregulation of MMP-9 expression is associated with the retinal degeneration in rodent RP models." (PMID 34270579, 2021). "In the present study using MIO-M1 culture system, we examined if MGCs express MMP-9 and TIMP-1 in response to proinflammatory conditions such as exposure to cytokines and oxidative stress that precipitates retinal degeneration." (PMID 34270579, 2021). "In the present study, we hypothesized that MGCs express endogenous MMP-9 and TIMP-1, the expression of which is altered in retinal remodeling during retinal degeneration." (PMID 34270579, 2021). "Associations between MMPs and the IL-1 family have also been found in other retinal degenerations, with increased levels of MMP-1, MMP-9, MMP-12, and IL-1β found in the vitreous of patients with POAG, as well as elevated MMP-9 and IL-1Ra observed in the vitreous and tears of ROP infants." (PMID 31379825, 2019).
schwannoma (5 papers, 2012 to 2026). A benign, usually encapsulated slow growing tumor composed of Schwann cells. "We previously demonstrated that adherent schwannoma is associated with elevated matrix metalloproteinase-9 (MMP-9) activity." (PMID 41756440, 2026). "Our in vivo data in a subcutaneous schwannoma mouse model suggests that a small molecule MMP9 inhibitor demonstrated significant anti-tumor effects and was well tolerated." (PMID 38887507, 2024). "Focusing on the role of ECM remodeling in VS progression, we demonstrate that MMP9 is an extracellular protease overexpressed in a mouse schwannoma model and in patients with adherent VS." (PMID 38887507, 2024). "MMP9 was the most highly upregulated protease in mouse schwannomas and was significantly enriched in adherent VS, particularly around tumor vasculature." (PMID 38887507, 2024). "MMP9 promotes schwannoma invasion and increases expression of cell adhesion molecules and can be targeted by a small molecule inhibitor in vivo." (PMID 38887507, 2024). "In summary, using a mouse schwannoma model and VS from patients, we identify MMP9 as a highly active protease during schwannoma growth and in adherent VS, representing an excellent classifying biomarker to distinguish adherent from nonadherent tumors." (PMID 38887507, 2024). "Our data suggests that schwannoma cells are one of the sources of MMP9, and schwannoma cells invade through collagen I due to MMP9-mediated collagen breakdown in vitro." (PMID 38887507, 2024). "Human schwannoma cells secreted MMP9 in response to TNF-α which promoted cellular invasion and adhesion protein expression in vitro." (PMID 38887507, 2024). "MMP9, produced by schwannoma cells, promotes schwannoma invasion in response to TNF-α and can be inhibited by targeting the eukaryotic translation initiation factor complex, eIF4F." (PMID 38887507, 2024). "To examine the spatial expression of MMP9 during mouse schwannoma progression, we stained tumors 1 week after implantation (small) and 3 weeks after implantation when tumors reached 1 cm in diameter (large)." (PMID 38887507, 2024). "MMP-9 cleaves N-cad to drive schwannoma proliferation through IL-6/STAT3 and NF-κB signaling." (PMID 41756440, 2026). "MMP9 initially concentrated around SOX-10 + schwannoma cells." (PMID 38887507, 2024). "Finally, to assess the therapeutic potential of MMP9 inhibitors in vivo, mice bearing subcutaneous schwannoma allografts were treated with silvestrol (1.5 mg/kg or 3 mg/kg) or MMP9-IN-I (3 mg/kg)." (PMID 38887507, 2024). "Together, our data provides mechanistic insight into the function of MMP9 in enhancing schwannoma cell invasion and adhesion, identifies eIF4 complex as a regulator of MMP9, and provides proof-of-concept data on the therapeutic efficacy of inhibiting MMP9." (PMID 38887507, 2024). "We next examined the effect of MMP9 on schwannoma cell invasion in vitro." (PMID 38887507, 2024). "The therapeutic efficacy of MMP9 inhibition was evaluated in a mouse schwannoma model." (PMID 38887507, 2024). "MMP9 abundance was assessed in mouse and human schwannoma cell lines." (PMID 38887507, 2024). "Lastly, MMP9 inhibition decreased mouse schwannoma growth in vivo." (PMID 38887507, 2024). "Transwell studies were performed to evaluate the effect of MMP9 on schwannoma invasion in vitro." (PMID 38887507, 2024). "We next investigated the mechanism by which MMP9 activity could mediate schwannoma cell invasion and increased cellular adhesion." (PMID 38887507, 2024). "Treatment with MMP9 inhibitors reduced schwannoma growth in mice." (PMID 38887507, 2024). "Moreover, upregulation of MMP‐9 enhanced schwannoma cell migration and invasion in vitro." (PMID 39506612, 2025). "Schwannomas Group: ICAM-1 was the most expressed, with E-Selectin, MMP-9, PAI-1, and VCAM-1 showing moderate expression." (PMID 38306519, 2024). "MMP9 was strongly colocalized with CD31/PECAM1 + endothelial cells and S100B + schwannoma cells." (PMID 38887507, 2024).
small cell lung carcinoma (5 papers, 2017 to 2022). Small cell lung cancer (SCLC) is a highly aggressive malignant neoplasm, accounting for 10-15% of lung cancer cases, characterized byrapid growth, and early metastasis. "Firstly, the basic expression levels of MMP9 mRNA and MMP9 protein in small cell lung cancer cells were detected by real-time fluorescence quantitative PCR and immunohistochemistry." (PMID 35431936, 2022).
steatosis (5 papers, 2019 to 2024). Increased lipid within the cytoplasm of cells. "MMP9 expression was significantly increased in both patients with steatosis and NASH." (PMID 37445827, 2023). "The analysis of genes identified in NAFL-Steatosis patients and NAFL-NASH patients (n = 58 genes) and in NASH patients (n = 141 genes) with high MMP9 level showed that 4 genes, FABP4, MMP9, HELLS and TREM2, were shared between these three groups of patients." (PMID 31874999, 2019). "Indeed, serum concentrations of MMP2, MMP9, TIMP1, TIMP2, MMP7, TGF-β1 and -β2 were found to be significantly higher in NAFLD patients compared to controls, yet these markers are unable to distinguish between steatosis and steatohepatitis." (PMID 37445827, 2023). "Moreover, the levels of the 12 serum-based markers were examined in relation to the CAP values; while MMP-9 levels were significantly lower, keratin-18 and ghrelin levels were significantly higher in patients with steatosis >S1 (CAP ≥302dB/m) than those without." (PMID 34813621, 2021).
stenosis (5 papers, 2021 to 2025). "Furthermore, NINJ1 and MMP9 are independent risk factors for plaque enhancement, arterial stenosis, and positive vascular remodeling." (PMID 40356625, 2025). "An earlier study has identified MMP9 as a pathogenetic factor for calcified aortic valve stenosis, and inhibition of MMP9 attenuates reactive oxygen species production and calcium deposition by improving the mitochondrial morphology and metabolism in calcified aortic valve interstitial cells." (PMID 37264340, 2023). "MMP9 protein increases indicate an escape from the modulatory actions of tissue inhibitors of MMPs (TIMPs), leading to the destruction of the tissue structure, and are observed in aortic valve stenosis, in concordance with the functional results obtained herein." (PMID 35631662, 2022). "Nishiguchi's23 study showed a higher MMP‐9 level in post stent STEMI patients, additionally in triple vessel stenosis patients." (PMID 33381894, 2021).
temporal lobe epilepsy (5 papers, 2013 to 2022). A localization-related (focal) form of epilepsy characterized by recurrent seizures that arise from foci within the temporal lobe, most commonly from its mesial aspect. "They found that the phosphorylation of ASK1 and the expression of MMP9 in hippocampus significantly increased in temporal lobe epilepsy, and the upregulation of MMP9 expression was caused by activation of ASK1." (PMID 35707480, 2022). "In two animal models of temporal lobe epilepsy, the kainic acid model and the pentylenetetrazole kindling model, these authors demonstrated decreased sensitivity in MMP-9 knockout mice but increased sensitivity in transgenic rats overexpressing MMP-9." (PMID 26567100, 2014). "It has been proposed that MMP-9 is involved in aberrant synaptic formation in hippocampi of patients with temporal lobe epilepsy." (PMID 23829879, 2013). "Consequently, MMP-9 is the first and only gene for which this correlation is found in human temporal lobe epilepsy." (PMID 27505431, 2016). "Our results revealed that DNA hydroxymethylation, which is the other epigenetic mechanism capable of controlling brain gene expression, is not involved in the regulation of MMP-9 hippocampal expression in during rat epileptogenesis and in human temporal lobe epilepsy." (PMID 27505431, 2016).
abortion (4 papers, 2021 to 2025). the ending of pregnancy by removing a fetus or embryo before it can survive outside the uterus. "Our Mendelian randomization analysis revealed that MMP9 andDC-SIGN were associated with increased spontaneous abortion risk, while HBAZ andNELL1 demonstrated a protective effect." (PMID 40674570, 2025). "Research has suggestedthat functional gene polymorphisms of MMP9 -1562 C/T might be associated with anincreased risk of Idiopathic recurrent spontaneous abortion in women.Moreover, a rise in MMP-9 concentrations has been linked to spontaneous abortion." (PMID 40674570, 2025). "MMP9 and DC-SIGN were associated with increased spontaneous abortion risk(OR=1.11(1.03-1.19), P=3.70x10-3; OR=1.09(1.02-1.16),p=9.89x10-3), while HBAZ and NELL1 hadprotective effects (OR=0.96(0.94- 0.99),p=5.20x10-3; OR=0.94(0.9-0.98),p=8.54x10-3)." (PMID 40674570, 2025). "In this study, administration of ZYPs significantly decreased the expression of TGF-β in the first oestrous cycle after induced abortion and increased the expression of MMP-9." (PMID 34711116, 2021). "Supporting this hypothesis, a previous study documented that overexpression of TNF-α, reduce MMP-2 and MMP-9, while an aggravation of the severity of abortion in rats further prompted TNF-α expression that sequentially decreased MMP-2 and MMP-9 levels." (PMID 35622593, 2022).
abscesses (4 papers, 2012 to 2026). "The results of binary regression analysis that indicated GCF sclerostin and GCF MMP-9 together have a significant effect on AP-related abscess formation is further evidence of a relationship between these two bioactive molecules in terms of bone resorption." (PMID 40323540, 2026). "Compared with the healthy control, significant upregulation in the gene expression of CYP4F3, VEGF, IL-8, TLR2 (P < 0.0001), and MMP-9 (P < 0.001) was found in the abscesses." (PMID 34539639, 2021). "Therefore, longitudinal studies following patients over time will be necessary to determine whether changes in sclerostin, PGE2, RANKL, and MMP-9 levels precede or result in AP severity and abscess formation." (PMID 40323540, 2026). "Accordingly, since GCF RANKL, GCF MMP-9, serum sclerostin, and serum PGE2 had AUC values of < 0.70, they were deemed unable to determine abscess formation in AP." (PMID 40323540, 2026). "Regression analysis performed in this study determined that a model consisting of OHI score, GCF sclerostin, GCF MMP-9, and GCF PGE2 tests could predict abscess formation related to AP severity with an accuracy of approximately 80.8%." (PMID 40323540, 2026). "However, since the correlation between PAI-abscess score and GCF RANKL and GCF MMP-9 was less than 0.30, it was considered insignificant." (PMID 40323540, 2026). "Furthermore, when used in combination, OHI score, GCF sclerostin, GCF MMP-9, and GCF PGE2 levels can predict the severity of AP-related abscess formation with approximately 80.8% accuracy." (PMID 40323540, 2026).
alcohol (4 papers, 2017 to 2025). "The protein expression of MMP-9 was closely associated with lgfAv-induced gastroprotection against alcohol-induced gastric lesions." (PMID 28874080, 2017). "Additionally, MMP9 polymorphisms, such as the C/T variant, have been linked to alcohol dependence and elevated serum MMP9 levels." (PMID 39518903, 2024). "Furthermore, a genetic polymorphism for MMP-9 is associated with alcoholism." (PMID 34054408, 2021). "According to the obtained results, MMP-9 levels in the plasma of patients suffering from alcohol dependency are much higher than the MMP-9 concentrations of the apparently healthy donors, irrespective of the level of intoxication." (PMID 39997037, 2025). "Furthermore, TIMP-1 was downregulated while MMP9 levels were elevated in subjects with alcohol intoxication in our study." (PMID 39518903, 2024).
anaplastic thyroid cancer (4 papers, 2012 to 2021). "OB3 induced only MMP2 significantly and MMP9 marginally in anaplastic thyroid cancer cells." (PMID 27050378, 2016). "In anaplastic thyroid cancer cells, leptin induced the expression of MMP2, and MMP9 which are involved in the invasion of cancer cells." (PMID 27050378, 2016). "In summary, leptin in anaplastic thyroid cancer cells not only increased expression of MMP2, MMP9 and VEGF in the current studies, supporting angiogenesis, but also induced cancer cell invasiveness and reduced adhesion." (PMID 27050378, 2016). "PLK1 siRNA suppressed the cell invasion of undifferentiated thyroid carcinoma, and CD44v6, MMP-2 and MMP-9 contributed to the regulation of cell invasion of undifferentiated thyroid carcinoma via PLK1." (PMID 23226764, 2012).
angiosarcoma (4 papers, 2013 to 2016). A malignant tumor arising from the endothelial cells of the blood vessels. "VEGF, MMP-9, and IL-6 are highly expressed by hemangiosarcoma tumor cells, suggesting that hemangiosarcomas use these factors to alter their tumor microenvironment (TME) and promote tumor growth." (PMID 29061946, 2015). "Such inhibition on angiosarcoma cell invasion may be due to decreased protein expression of MMP9 and reduced hydrolysis of extracellular matrix." (PMID 27531900, 2016).
Atherosclerotic lesion (4 papers, 2011 to 2024). A lesion associated with atherosclerosis, a multifactorial and multipart progressive disease manifested by the focal development within the arterial wall of lesions, that ranges from the development of a fatty streak, plaque progression, and plaque disruption. "In human and mouse atherosclerotic lesions, Mmp-9 has been shown to participate in SMC migration." (PMID 22073227, 2011).
autoimmune myocarditis (4 papers, 2019 to 2024). Autoimmune myocarditis is an autoimmune disease that affects the heart. "The current results together with the previous ones indicate that simvastatin in the autoimmune myocarditis model affects not only MMP-9 activity but also the activity of the RhoA/ROCK pathway." (PMID 38540212, 2024). "Increased activation of MMPs such as MMP-3 and MMP-9 were also observed in experimental mouse autoimmune myocarditis." (PMID 34680049, 2021). "They provide a new insight into the molecular pathology of autoimmune myocarditis and also make an important contribution to the study of the relationship between two important pathogenetic pathways resulting from the activation of MMP-9 and RhoA." (PMID 38540212, 2024). "On the other hand, our study using an autoimmune myocarditis model in BALB/c mice showed that MMP-2, but not MMP-9, is activated in the pathogenesis of DCM, consistent with a previous observation in human DCM27." (PMID 34702968, 2021).
basal cell carcinoma (4 papers, 2013 to 2026). A carcinoma involving the basal cells. "The aim of this study was to compare the expressions of mRNA for metalloproteinases (MMP-2 and MMP-9) and type IV collagen in two different histological types of basal-cell carcinoma (BCCs; nodular and infiltrative) and in normal tissues from the tumor interface." (PMID 27406386, 2016). "In human basal cell carcinoma (BCC), M2 TAMs enhanced the potential of invasion and angiogenesis through a COX-2-dependent pathway, resulting in the elevated release of VEGF-A, bFGF and MMP-9 from BCC cells." (PMID 28081243, 2017).
benign breast tumors (4 papers, 2019 to 2023). "In particular, MMP-11, but also MMP-2, and MMP-9 were higher in BC when compared with benign breast tumors." (PMID 37798646, 2023). "MMP-9 expression was higher in luminal A-like BC subtypes compared to benign breast tumors and other subtypes." (PMID 37798646, 2023). "In this study, there was a higher mRNA expression of MMP-2 and MMP-9 in BC patients compared to benign breast tumors, but no statistical significance." (PMID 37798646, 2023). "No statistical differences were observed between MMP-9 concentrations in the group with benign breast tumor and healthy subjects." (PMID 33371324, 2020).